INS (insulin)
Diseases named in the same sentence as INS in open-access papers (continued):
Sharing a sentence is not in itself a finding about the gene and the disease.
Hyperglycemia (continued). "Moreover, Opa1 deletion in pancreatic β cells impairs glucose-stimulated adenosine triphosphate (ATP) production and insulin secretion, which subsequently develops into hyperglycemia." (PMID 31551926, 2019). "Primarily, they may promote hyperglycemia by increasing the calcium concentration in pancreatic β islet cells, leading to a decrease in insulin release, or by decreasing GLUT 4-mediated peripheral glucose uptake." (PMID 31052590, 2019). "The present study was designed to explore whether PNS decrease hyperglycemia by improving insulin sensitivity in skeletal muscle and to elucidate the molecular mechanisms." (PMID 30945455, 2019). "These discrepancies may be explained by the evaluation of a group of patients of mixed metabolic disease statuses in these studies, complicating the evaluation of serum VEGF levels, as serum VEGF levels are induced by insulin and hyperglycemia." (PMID 31203592, 2019). "Essentially, they continuously mentally predict the future evolution of blood glucose levels and then decide, following medical staff advice, when and how much insulin is required to maintain metabolic control and avoid eventual hyperglycemia or hypoglycemia that triggers subsequent hyperglycemia." (PMID 31623111, 2019). "It has been acknowledged that DM shows hyperglycemia/hyper-insulin in peripheral tissues." (PMID 31551793, 2019). "In addition to post-prandial hyperglycaemia patients in the highest tertile of any of the anthropometric measurements studied, had a significantly decreased insulin sensitivity and ß-cell function as compared with those in the lowest tertile." (PMID 30777085, 2019). "Vanadium compounds are nonspecific phosphotyrosine phosphatase inhibitors that have proven insulin-mimetic and/or insulin enhancing activity either in vitro or in vivo, countering hyperglycemia observed in T1DM human subjects and also maintaining glucose homeostasis in T2DM subjects." (PMID 31658729, 2019). "The patient’s severe hyperglycemia was controlled with an insulin drip." (PMID 31542681, 2019). "Hyperglycemia and high serum insulin levels caused the arteries to become more rigid regardless of the subject’s race or gender in insulin-dependent diabetic patients." (PMID 31450550, 2019). "In patients with type 1 diabetes (T1D), who have little or no production of insulin, there are several metabolic alterations as hyperglycemia, weight loss and enhanced lipolysis with augmented lipotoxicity." (PMID 31920961, 2019). "New data suggest that exosomes (i.e., membrane-derived nanovesicles) may play a role throughout gestation, including mediation of a placental response to hyperglycemia and insulin sensitivity." (PMID 31828161, 2019). "T2DM is characterized by hyperglycemia and low insulin relative to the metabolic demand." (PMID 31258514, 2019). "Insulin administration effectively controls both hyperglycaemia and ketosis." (PMID 31089886, 2019). "Glinides, therefore, increase insulin secretion earlier and lower postprandial hyperglycemia." (PMID 31486247, 2019). "The IR, characterized by hyperglycemia and compensatory hyperinsulinemia—as consequence of the impairment of the insulin signaling pathway—represents the main feature of metabolic syndrome and type 2 diabetes mellitus, and a high-risk factor for cardiovascular diseases as well." (PMID 31835800, 2019). "It has been suggested that hyperglycemia in T2DM enhances the metabolic load on β-cells, causing an increase in the production of reactive oxygen species (ROS), in part, due to the oxidative nature of insulin protein folding and glucose metabolism." (PMID 30679186, 2019). "We hypothesized that olanzapine can increase hyperglycemia by suppressing insulin secretion from pancreatic β-cells via blockade of multiple monoamine receptors." (PMID 31712714, 2019). "Insulin dysfunction, hyperglycemia, impaired cholinergic system, and inflammation in DM may affect synaptic plasticity, learning and memory, and ultimately result in AD." (PMID 31551793, 2019).
Hyperglycemia (continued). "To reduce the risk of hyperglycemia in this study, first the participants did not have to reduce basal insulin before and during the competition due to the plan we had about using an extended amount of CHO throughout the race." (PMID 31496994, 2019). "Inappropriate therapeutic decisions regarding insulin dosing may lead to significant hyperglycemia or hypoglycemia." (PMID 30871141, 2019). "In diabetic mice, the PI transplants produced insulin and partiallycontrolled the hyperglycemia." (PMID 31450972, 2019). "Our findings were in agreement with earlier observations that MLD-STZ injections may lead to hyperglycemia evident in C57BL6J mice, indicating that STZ induction displayed β cell mass loss and then insulin insufficiency, leading to hyperglycemia." (PMID 31581697, 2019). "Moreover, resveratrol has been shown to normalize hyperglycemia, improve insulin sensitivity, and lower hepatic glucose production through the activation of SIRT1." (PMID 30800211, 2019). "CSII therapy following the presented algorithm is easily feasible and safe in patients with hyperglycemia immediately after kidney transplantation, clearly improving glycemia over the first week of therapy even when compared to basal insulin isophane treatment." (PMID 29518094, 2018). "In recent years, optimized differentiation protocols have been successfully developed to generate glucose-responsive insulin-secreting cells in vitro from hESC/iPSC, which express mature β cell markers, and transplantation of these cells has been shown to ameliorate hyperglycemia in diabetic mice." (PMID 30594258, 2018). "Insulin was used to control hyperglycemia (mean = 265±81mg/dl)." (PMID 30252878, 2018). "Furthermore, glucose stimulated insulin secretion, glucose tolerance and hyperglycemia were improved in EGCG treated db/db mice, which is a model for T2D44." (PMID 29348618, 2018). "Every 1% increase in HbA1c was associated with a 300% (95% CI: 2.35–3.87) increase in the odds of using basal-bolus insulin therapy, and every 10% increase in the incidence of hyperglycemia increased the chance of administering basal-bolus insulin therapy by 50% (95% CI: 1.35–1.66)." (PMID 29255628, 2018). "It has been reported that glucotoxicity and hyperglycemia initiation might appear due to the reduction of insulin, PDX1, and β-cell deregulation of glucose transporters on membrane." (PMID 29805204, 2018). "It was recognised in the 1920s that insulin deficiency was the cause of diabetes, and that administration of pancreatic extracts containing insulin could successfully treat the hyperglycaemia." (PMID 29412829, 2018). "According previous studies, the hyperglycemia state in fish induced by high-carbohydrate intake could stimulate insulin synthesis and release." (PMID 29740344, 2018). "Acylated ghrelin induces hyperglycemia and reduces the insulin secretion, and insulin sensitivity." (PMID 30534079, 2018). "Vehicle treated STZ-CD1 mice developed severe hyperglycaemia with near-absent circulating insulin and widespread beta cell loss in association with hyperglucagonaemia and expanded islet alpha cell mass." (PMID 30228292, 2018). "Additionally, when the fetus receives excess glucose due to maternal hyperglycemia (and corresponding increases in glucose transport), the elevated insulin production by maternal/fetal islets can accelerate fetal growth." (PMID 30400566, 2018). "Studies involving CGM have also shown that while insulin adjustment may be a useful tool for managing glycemia, it may result in an unwanted increase in hyperglycemia unless carbohydrate intake is also adequately managed." (PMID 30081478, 2018). "Furthermore, the authors showed that both hyperglycemia and direct activation of the hexosamine biosynthesis pathway by glucosamine determines reduction in insulin-stimulated phosphorylation of eNOS by increased O-GlcNAcylation of key signaling molecules." (PMID 29681862, 2018).
Hyperglycemia (continued). "The primary aim of this study is to determine whether the administration of a DSF reduces insulin administered to critically ill patients with hyperglycemia during enteral nutrition compared to a standard liquid nutritional formula over a 48-hour period." (PMID 29631990, 2018). "In insulin pump systems with predictive low glucose management, however, hypoglycemia or hyperglycemia could be inadvertently induced because suspension or resumption of insulin delivery may be inadequate." (PMID 30067409, 2018). "The results showed CFD induced hyperglycemia and inhibited hepatic insulin pathway." (PMID 30153273, 2018). "Although there is a slightly higher risk of hyperglycaemia, this can be effectively treated with insulin with no long-term effects." (PMID 29402313, 2018). "In addition, blood glucose concentrations vary markedly in critically ill patients, even when using continuous feeding and insulin infusions, and blood glucose values and incidence of hyperglycaemia have a circadian rhythm in critically ill patients." (PMID 29713388, 2018). "However, chickens constitutively exhibit “hyperglycaemia” (>200 mg/dL), despite rather normal levels of a hyperactive endogenous insulin." (PMID 30018639, 2018). "Intensive insulin secretion and islet beta cell proliferation can provide a temporary buffer, but over time, blood glucose will eventually break the limit and develop into hyperglycemia." (PMID 30618599, 2018). "Carbohydrates are the main source of glucose for metabolism, and reducing their intake may lead to a decrease in insulin requirements and an improvement in insulin sensitivity that results in reduction of postprandial hyperglycemia." (PMID 30328516, 2018). "Chronically, hyperglycemia may promote, in a more advanced stage of T2D, pancreatic islet damage and a subsequent decline in insulin secretion." (PMID 30116154, 2018). "Generally, high dietary carbohydrate intake usually induces a hyperglycemia state of fish, as might in turn stimulate insulin synthesis and secretion." (PMID 30254587, 2018). "Moreover, we demonstrate that highly dosed d-serine induces hyperglycemia, and strongly impairs glucose tolerance due to impaired insulin secretion from pancreatic beta cells." (PMID 30093356, 2018). "For example, although reduction of acromegaly disease activity might lead to improvements in insulin sensitivity, worsening of hyperglycaemia can occur during therapy, largely owing to inhibition of insulin secretion by SRLs (MQ)." (PMID 30050156, 2018). "The pathophysiology behind postoperative hyperglycemia is partly induction of a hyperglycemic response by cortisol and growth hormone and partly insulin resistance and inhibition of insulin secretion, all induced by the neuroendocrine and metabolic stress response to surgery." (PMID 29843742, 2018). "Besides, in insulin-responsive tissues, JNK is activated by fatty acids, insulin, hyperglycemia, and inflammatory cytokines." (PMID 29484304, 2018). "As a result, hyperglycemia and hyperinsulinemia occur because of less glucose uptake from metabolic tissues in response to insulin and the triggering of pancreatic beta cells to secrete more insulin to control glucose homeostasis." (PMID 30134566, 2018). "Re- nutrition re-initiates metabolic pathways; in fact, hyperglycemia stimulates insulin secretion." (PMID 29382373, 2018). "Obese, insulin resistant and diabetic patients display impaired glycolysis and dysfunctional mitochondrial oxidation, which are major contributors to impaired glucose disposal/utilization and hence to hyperglycemia." (PMID 29315239, 2018). "The structural and functional damages of β-cells and target tissue of insulin could be the main aim of therapy protocol of hyperglycemia to protect β-cells and lessening of DM." (PMID 29805204, 2018). "After intraportal infusion of GIP, acute hyperglycemia increased insulin concentrations." (PMID 29673130, 2018).
Hyperglycemia (continued). "Insulin has several important functions, such as regulation of lipids synthesis, regulation of enzymatic activity and above all regulation of blood glucose levels and prevention of hyperglycemia." (PMID 29780554, 2018). "For the majority of critically ill patients and non-critically ill patients, at a blood glucose value of 10.0 mmol/L insulin therapy should be initiated for treatment of persistent hyperglycemia with the aim of achieving target glucose level in the range between 7.8 and 10.0 mmol/L." (PMID 29508275, 2018). "Unpredicted changes in insulin requirements expose patients to hypoglycemia or hyperglycemia." (PMID 29682315, 2018). "However, as with variations in hyperglycemia frequency, differences were detected in the use of basal-bolus insulin therapy according to surgical service." (PMID 29255628, 2018). "Furthermore, when beta cells are destroyed, insulin secretion is reduced, resulting in hyperglycemia." (PMID 29849938, 2018). "Indeed, previous studies on diabetic subjects have shown that the intranasal administration of INS reduced postprandial hyperglycemia by up to four h." (PMID 30274197, 2018). "The Px rats had hyperglycemia due to increased insulin resistance and decreased insulin secretion." (PMID 30041479, 2018). "However, they only lasts for 24 h and start decreasing at the end hours, thereby leading to occasional hyperglycemia just before the next insulin dose & requiring next dose to be given at fixed time of the day." (PMID 30069184, 2018). "Our results showed a protective effect of extracts against hyperglycemia-induced oxidative stress through the modulation of RINm5f beta cell cytotoxicity, generation of ROS, insulin release, caspase-3 activation, pro-oxidant and antioxidant defense, and status of the cells." (PMID 29558444, 2018). "Review of a number of reports also suggests that insulin-insensitivity and hyperglycemia (glucose toxicity and high circulating glucose levels) alter mTOR complexes (mTORC1, mTORC2) and mediate several interdependent pathways of metabolism, ribosomal biogenesis and autophagy." (PMID 29961900, 2018). "Hyperglycemia causes glucose autoxidation, impaired mitochondrial bioenergetics and induces reactive oxygen species (ROS) production, leading to an impairment of intracellular pathways (i.e., JAK/STAT, JNK, p38, ERK/MAPK) and to insulin resistance." (PMID 29300317, 2018). "Although the precise mechanisms still remain unclear, improvement of both hyperglycemia and insulin sensitivity by CANA could contribute to decreasing GSSG/GSH ratio in adipose tissue." (PMID 29402900, 2018). "After weaning, many changes occur which include hyperglycemia, impaired glucose-induced insulin secretion (due to defective prenatal β-cell proliferation and reduction in β-cell mass), reduced insulin sensitivity in the liver, and moderate insulin resistance in peripheral tissues." (PMID 29850600, 2018). "Yet, this remains to be proven by randomized trials, since the pathophysiological mechanisms linking hyperglycemia and acute ischemia are complex and still debated, and intensive insulin treatment may paradoxically increase infarct growth." (PMID 29777362, 2018). "The guidelines of the American Society for Parenteral and Enteral Nutrition suggest that newborns should receive intravenous lipids when dextrose is infused, as glycerol is the predominant gluconeogenic substrate and to consider insulin in cases of prolonged hyperglycemia." (PMID 29880053, 2018). "Management of hyperglycemia often involves exogenous insulin." (PMID 29631990, 2018). "The reduced placental oxidative stress could be indirectly due to the antihyperglycaemic action of propolis and insulin as there is a presence of placental oxidative stress in mother with hyperglycaemia." (PMID 30518366, 2018).
Hyperglycemia (continued). "Previously, vatinoxan is shown to prevent the hyperglycaemia, increase of plasma lactate concentration and the decrease of insulin and non-esterified free fatty acids (FFAs) caused by α-2 adrenoceptor agonists in different species." (PMID 29743097, 2018). "Moreover, the authors of the United Kingdom Prevention Study considered hyperglycaemia to be a more relevant predictor of coronary events in the course of T2D when compared with increased insulin levels." (PMID 29302846, 2018). "The progress of disease is very simple; lack of insulin causes hyperglycemia and inability of glucose to enter the cell." (PMID 29619008, 2018). "Besides Leonard, Joe Gilchrist, a diabetic doctor, was another patient who underwent the innovative treatment, and was also the first patient to suffer from hypotensive hyperglycaemia, one of the side-effects of insulin therapy." (PMID 30405529, 2018). "This fear of hypoglycemia frequently results in insufficient insulin supplementation, which may lead to hyperglycemia and diabetic ketoacidosis (DKA)." (PMID 30069184, 2018). "Moreover, the overexpression of GPX1 in mouse increases body weight and fat content, hyperglycemia, and hyperinsulinemia and reduces insulin sensitivity." (PMID 29675131, 2018). "Insulin is a key regulatory polypeptide that is secreted from pancreatic β-cells and has several important effects on the synthesis of lipids, regulation of enzymatic activities, blood glucose levels and the prevention of hyperglycemia." (PMID 29780554, 2018). "In addition, the β-cell can become overwhelmed by prolonged exposure to hyperglycemia; the resulting glucotoxicity generates oxidative stress within the β-cell, leading to decreased survival and reduced glucose stimulated insulin secretion." (PMID 30400566, 2018). "We found that STZ induced sustained fasting hyperglycemia in rats, low serum insulin levels, and poor glucose response, likely due to loss of pancreatic beta cells that led to a significantly reduced beta-cell mass, assessed 6 weeks after STZ treatment at which point the rats were sacrificed." (PMID 30346929, 2018). "CRS impairs glucose-sensitive neurons of acNTS and thus leads to insulin-resistant hyperglycemia." (PMID 30618599, 2018). "The beta cells in newly diagnosed T1D patients may have dedifferentiated upon hyperglycemia as suggested by some studies, and could therefore resume beta cell phenotype upon insulin treatment and normoglycemia." (PMID 30386256, 2018). "These drugs are able to increase insulin release only in the context of hyperglycemia." (PMID 30425649, 2018). "The study described in the present report was undertaken to evaluate a hypothesis that an orally administered preparation of fenugreek seeds reduces hyperglycemia through insulin sensitization." (PMID 29518003, 2018). "However, unlike the patients on general surgery, only 43% of neurosurgery patients, 49% of orthopedics patients and 48% of urology patients whose hyperglycemia frequencies were in the highest tertile received basal-bolus insulin therapy." (PMID 29255628, 2018). "Possible explanations for the change in neuronal activation could be an effect of an increase of fetal glucose and/or insulin, or fetal insulin resistance induced by maternal hyperglycemia." (PMID 30524370, 2018). "In conclusion, this is the first report of a PAX4 gene KO model in rabbits, including characteristics of growth retardation, persistent hyperglycemia, decreased number of insulin-producing β cells, increased number of glucagon-producing α cells and typical DM associated phenotypes." (PMID 29950431, 2018). "The lower use of basal-bolus insulin in 2015, and the greater frequency of hyperglycemia could be evidence of the need to go revisit how inpatient hyperglycemia treatment strategies are being taught." (PMID 29255628, 2018). "In addition, d-serine leads to diet-independent hyperglycemia due to blunted insulin secretion from pancreatic beta cells." (PMID 30093356, 2018).